SLC4A1AP (solute carrier family 4 member 1 adaptor protein)
Synonyms: HLC3; kanadaptin
Tractability: Antibody: its Gene Ontology location is reachable by antibodies, with high confidence. PROTAC: UniProt records ubiquitination sites on it; ubiquitination databases record sites on it; its protein half-life has been measured.
Gene: Protein-coding gene on chromosome 2 (27,663,426 to 27,695,366, forward strand). Ensembl gene ENSG00000163798.
Subcellular location: Nucleus; Cytoplasm
Subcellular location (Human Protein Atlas): Nucleoplasm; Plasma membrane; Vesicles
Gene Ontology:
Molecular function: protein binding; mRNA binding
Cellular component: nucleoplasm; cytoplasm; nucleus
Genetic constraint (gnomAD): Loss-of-function variants: 35 observed, 56.98 expected, observed/expected ratio (o/e) 0.61, 90% interval 0.47 to 0.81. The upper end of that interval is the gene's LOEUF score, 0.81, which puts it in group 3 of 6, group 1 being the genes least tolerant of losing a copy. Missense variants: 583 observed, 643.02 expected, observed/expected ratio (o/e) 0.91, 90% interval 0.85 to 0.97. Synonymous variants: 225 observed, 235.95 expected, observed/expected ratio (o/e) 0.95, 90% interval 0.85 to 1.07.
Homologues: Orthologues: chimpanzee SLC4A1AP (99% identical), macaque SLC4A1AP (97% identical), pig SLC4A1AP (84% identical), guinea pig SLC4A1AP (82% identical), rabbit SLC4A1AP (81% identical), rat Slc4a1ap (81% identical), mouse Slc4a1ap (80% identical), tropical clawed frog slc4a1ap (53% identical), zebrafish slc4a1ap (48% identical), Caenorhabditis elegans ZK632.2 (29% identical). Paralogues in human: PPP1R8 (14% identical), SNIP1 (11% identical).
Diseases named in the same sentence as SLC4A1AP in open-access papers:
SLC4A1AP is named in the same sentence as 3 diseases in open-access papers, as found by Europe PMC text mining. Sharing a sentence is not in itself a finding about the gene and the disease. The quoted sentences say what the papers report.
Hypertension (1 paper, 2021). The presence of chronic increased pressure in the systemic arterial system. "To validate results from available databases, we examined the expression of YWHAZ and SLC4A1AP, the best candidate RGs, in FFPE-derived specimens from patients with hypertension (HT, n = 11) and non-diseased controls (NDC, n = 5)." (PMID 34882702, 2021).
hypertensive nephropathy (1 paper, 2021). Kidney damage that results from chronically elevated blood pressure; complications include glomerular damage resulting in proteinuria and hematuria. "Expression variability of 4 candidate genes (YWHAZ, SLC4A1AP, RPS13 and ACTB) was further examined by qPCR in biopsies from patients with hypertensive nephropathy (n = 11) and healthy controls (n = 5)." (PMID 34882702, 2021).
cancer (1 paper, 2019). A tumor composed of atypical neoplastic, often pleomorphic cells that invade other tissues. "Among the acid-loading transporter genes, the expressions of SLC4A1AP, SLC4A2, and SLC4A3 are up-regulated or remain unaltered in cancer tissues vs. controls across most of the 14 cancer types." (PMID 31071451, 2019).